TLR4 (toll like receptor 4)
Diseases named in the same sentence as TLR4 in open-access papers (continued):
Sharing a sentence is not in itself a finding about the gene and the disease.
tumor (continued). "In the present study, we demonstrate that B16 cells (a mouse melanoma tumor line) expressing recombinant sCRT39-272 exhibit significantly more malignant behavior in mice, which is attributed to the ability of sCRT39-272 to expand and recruit MDSCs in a TLR4 and S100A8/9-dependent manner." (PMID 29075268, 2017). "Thus, sCRT39-272 could directly interact with MDSCs derived from tumor-bearing animals through TLR4, leading to production of S100A8/9, which in turn blocks MDSC differentiation." (PMID 29075268, 2017). "Serum TLR4 is the soluble form of its extracellular domain on cells, there is a hypothesis that the extracellular domain of TLR4 may crack from tumor cells with the development and metastasis of tumor." (PMID 29029545, 2017). "Paclitaxel brought out robust inflammatory responses and tumor growth in TLR4 positive cells, but not in TLR4 negative cells, indicating that TLR4 may be a underlying reason for the resistance to chemotherapy." (PMID 29029545, 2017). "Meanwhile, studies found that serum TLR4 maybe a biomarker of tumor metastasis and prognosis." (PMID 29029545, 2017). "Interestingly, PancO2 lysate could not inhibit LPS induced NO levels in these MΦ providing first evidence that TLR4 stimulation is decisive for the maintenance of M1 effector phenotype in Tumor induced MΦ (TIM)." (PMID 27511884, 2016). "We speculated that M3G, a metabolite produced in elevated concentrations following morphine administration, would further tip the balance of tumor macrophage polarization toward the M1 end of the phenotype spectrum via its reported ability to activate the TLR4." (PMID 27909407, 2016). "Conversely, our hypothesis is that TLR4 plays an important role in the innate immune system and that alteration of the structural function of this protein, which ultimately hampers immune surveillance in colon mucosa, may lead to tumor development." (PMID 26771524, 2016). "TLR4 activation may also lead to tumor regression by increasing vascular permeability." (PMID 26675260, 2016). "Therefore, increasing levels of serum sTLR4, by blocking the binding of TLR4 ligands to membrane-bound TLR4, may inhibit intracellular signaling through membrane-bound TLR4 and then dampen the pro-inflammatory tumor microenvironment." (PMID 27223258, 2016). "Interestingly, both LPS and LPS free Ff phages were demonstrated to mediate their anti-tumorigenic activity, at least in part, via TLR4 which might explain the similarities in their tumor inhibition mechanism." (PMID 26074908, 2015). "Our data showed that Sal-YB1 could upregulate TLR4 expression in the tumor tissues." (PMID 26286454, 2015). "TLR4 downregulation may have a specific role in limiting the progression of HBV-related tumor, while HBV-unrelated HepG2 cells cause tumor development in nude mice with or without TLR4 downregulation." (PMID 26514586, 2015). "In experiments to further help determine whether HMGB1 regulates VEGF-A in tumour angiogenesis, we applied the associated antibodies to co-cultured ECs, and VEGF-A concentrations were decreased by 2G7 mAb, TLR4 Ab and RAGE Ab, as demonstrated in Western blot analyses." (PMID 26099505, 2015). "Furthermore, HMGB1 could rapidly activate NFκB, a hallmark of TLR4/RAGE signaling, in DU145 tumor cells, as assessed by NFκBp65 phosphorylation." (PMID 26469759, 2015). "Additionally, certain studies have shown that the activation of TLR4 signaling may correlate with tumor progression." (PMID 24959291, 2014). "This tumor burden could be attenuated using TLR4-inhibiting antibody." (PMID 24887394, 2014). "TLR4 activation may also lead to tumour regression by increasing vascular permeability." (PMID 25179302, 2014). "Also, knockdown of TLR4 using siRNA in PC3 cells reduces tumor cell migration and invasion." (PMID 25101092, 2014).
tumor (continued). "Activation of the TLR4 signaling by Pac has been demonstrated in murine macrophages, transfected cell lines, and mouse tumor cell lines, although the results revealing involvement of TLR4 on the Pac effects on myeloid cells are controversial and might be concentration-dependent." (PMID 23441224, 2013). "These novel findings suggest signaling from the BALF milieu is involved in GJIC dysregulation associated with promotion and links gap junctions to pulmonary TLR4 protection in a novel ex vivo model that could assist in future potential tumor promoter screening." (PMID 25035812, 2013). "Recently, we have demonstrated that fusion of an antigen to the extra domain A from fibronectin (EDA) favours antigen targeting to TLR4-expressing DC, leading to their maturation and enhancing cross-presentation and immunogenicity of the antigen as well as the induction of antiviral/tumor immunity." (PMID 24093105, 2013). "Also TLR4 has been shown to be involved in tumor progression in different tumor models." (PMID 22470535, 2012). "Thus, it can be speculated that these cells release S100A9 that via interaction with TLR4 promote tumor growth." (PMID 22470535, 2012). "We next examined whether TLR4 expression influenced LPS-induced tumor cell metastasis in vivo." (PMID 22938142, 2012). "Furthermore, TLR4 has been shown to be involved in tumor progression, and we therefore wanted to investigate whether TLR4 expression could also influence tumor growth in the TRAMP tumor model." (PMID 22470535, 2012). "Consequently, a decreased interaction of tumor-derived HMGB1 with TLR4-expressing Treg might result in a decreased anti-tumor immune response in TLR4 Asp299Gly or Thr399Ile carriers which may result in a reduced DFS and OS." (PMID 21854645, 2011). "TLR-4 is a transmembrane pattern recognition receptor that provides a critical link between immune stimulants produced by microorganisms, in particular lipopolysaccharide, and the initiation of the innate immune reaction to foreign agents, but also to tumor cells." (PMID 21059221, 2010). "The interaction of HMGB1 protein released from dying tumor cells with TLR4 on DCs was required for the cross-presentation of tumor antigens and the promotion of tumor specific cytotoxic T-cell responses, which are selectively involved in the cross-priming of anti-tumor T lymphocytes in vivo." (PMID 20579387, 2010). "We observed that AC patients who had a percentage of TLR-4+ cells in the tumor stromal compartment, (mostly immune cells), lower than the median value had fewer relapses, and the relapses that occurred did so after a longer lag time that those AC patients with higher TLR-4 expression." (PMID 21059221, 2010). "Thus stimulation of tumour cell TLR-4 and subsequent NF-κB activation by systemic exposure to LPS in the perioperative period may accentuate tumour cell adhesion and invasion by a variety of mechanisms including activation of the u-PA and integrin systems." (PMID 19436306, 2009). "Thus, a direct link between tumor cell activation and LPS might be suggested because some tumor cells constitutively express TLR-4." (PMID 17156435, 2006). "Furthermore the TLR-signalling pathway may be manipulated by tumour cells in a manner analogous to the mouse mammary tumour retro virus which subverts the innate immune system through the TLR-4 dependent production of the immune suppressive cytokine IL-10." (PMID 16892041, 2006). "The innate immune Toll-like receptor 4 (TLR4) controls immune and inflammatory signalling in the tumour microenvironment." (PMID 42121921, 2026). "These molecules bind to receptors such as P2X7, TLR4, or LDL receptor‐related protein 1, thereby activating the immune system and enhancing anti‐tumor immune responses." (PMID 41560416, 2026). "RESULTS: TLR4 knockout markedly improved the efficacy of OXA in vivo, reducing tumor burden while simultaneously downregulating key inflammatory mediators and glycolytic markers." (PMID 41663949, 2026).
tumor (continued). "Tumor cells undergoing ferroptosis release HMGB1, which binds to TLR4 on myeloid cells, enhancing differentiation into mature cells." (PMID 40948759, 2025). "miR‐203 and miR‐212‐3p can be delivered from PC cells to DCs via exosomes, which down‐regulate TLR4 and MHC II, respectively, leading to impaired DC function and further promoting tumour immune evasion." (PMID 40579785, 2025). "In co-culture, M1 TAMs promote cancer cell apoptosis and inhibit invasion, while M2 TAMs drive tumor growth and metastasis via pathways like TLR-4/STAT-3, TLR-4/NF-κB, and Wnt/β-catenin." (PMID 41041128, 2025). "Insufficient Toll-like receptor 4 (TLR-4) signaling activation in tumor cells can result in inflammatory responses, which can lead to resistance to tumor cell death and more active proliferation and invasion." (PMID 40002869, 2025). "In conclusion, our study demonstrates that BGN is significantly upregulated in CAFs within the ESCC tumor microenvironment and promotes the proliferation and migration of ESCC cells through activation of the Erk and NF-κB pathways via TLR4 signaling." (PMID 41465449, 2025). "PRDX1, a primary target of peroxisome-derived H2O2, supports tumor growth and angiogenesis in PC3-M xenografts by promoting vascular endothelial growth factor (VEGF) expression in a Toll-like receptor 4 (TLR4)-dependent manner." (PMID 40647540, 2025). "By differentially modulating the TLR4 and IFN-γ/STAT1 signaling axes, CCRL2 acts as a context-specific regulator of innate immune responses and tumor architecture." (PMID 40867595, 2025). "Extracellular HMGB1 has been shown to interact with multiple cell surface receptors, most notably, receptor for advanced glycation end products (RAGE) and Toll-like receptor 4 (TLR4), to promote inflammation and tumor growth." (PMID 41109352, 2025). "Following TAK-242 treatment to inhibit TLR4 signaling, the HMGB1-induced M1 macrophage polarization stimulated with the supernatants from ADVNE− or ADVPPE-treated tumor cells was abrogated." (PMID 40082916, 2025). "Alpha 1-acid glycoprotein (AGP) activates TLR4 through CD14, modulating PD-L1 expression and IL-6 production, thus enhancing tumor immune suppression." (PMID 40948759, 2025). "Numerous studies demonstrate that HMGB1, upon release from stressed or dying tumor cells, engages RAGE, TLR4, or TNFR1 to initiate canonical NF-κB activation, resulting in phosphorylation of IKKα/β, degradation of IκBα, and nuclear translocation of p65." (PMID 41465435, 2025). "In PDAC, gut-derived LPS (≥500 pg/mL in the TME) exerts dual effects: via TLR4/MyD88/AKT/NF-κB signaling, it upregulates tumor PD-L1 to promote immune evasion, yet recruits CD3+CD8+ T cells for antitumor activity." (PMID 41181090, 2025). "In breast cancer cells, activation of TLR2 and TLR4 stimulates NF-κB, regulating the secretion of cytokines such as IL-6, TGF-β, VEGF, and MMP9, promoting tumor invasion, migration, and progression." (PMID 41200171, 2025). "In this study, paclitaxel/ATP release induced the inflammasome activation via TLR4 that led to the phosphorylation of IkB and Jun N-terminal kinase (JNK) and the upregulation of pro-inflammatory cytokines in favor of tumor growth." (PMID 39857785, 2025). "By combining ICD-mediated chemotherapy, TLR4-STING co-activation, and PD-1/PD-L1 blockade, this system not only enhanced immediate tumor cytotoxicity but also established a long-lasting anti-tumor immune memory." (PMID 40264674, 2025). "In parallel, TLR4/MYD88/NF-κB signaling augments pro-inflammatory cytokines and cooperates with Wnt pathway, together reinforcing epithelial proliferation and a tumor-permissive niche." (PMID 41356485, 2025). "For example, Zhang and his colleagues introduced the intracellular TIR domain of TLR4 directly into the CAR to develop the second-generation CAR-M, which promotes an M1-like pro-inflammatory state, enhancing anti-tumor effects." (PMID 40520002, 2025).
tumor (continued). "LP17-mediated TREM1 inhibition attenuated PMT through modulation of the TLR4/PI3K/AKT/mTOR pathway and reduced tumor growth in vivo." (PMID 41394801, 2025). "We treated tumour-bearing wild-type mice with the small-molecule TLR4 inhibitor TAK-242 only during anti-PD-1 therapy and examined the effect of treatment on tumour growth." (PMID 39929976, 2025). "NET formation by vital NETosis boosts HMGB1 production in tumor cells, activating TLR9-dependent pathways and the TLR4/9-COX2 pathway, which improve tumor cell survival and invasion." (PMID 40655142, 2025). "The results showed that TLR4 was expressed in tumor tissues, LLC cells and A549 cells and that TLR4 expression increased with increasing LPS dose." (PMID 40817754, 2025). "CpG oligodeoxynucleotides (ODNs), which modulate TLR-4-related pathways to some extent despite being TLR-9 agonists, are being explored for their potential to enhance the anti-tumor immune response." (PMID 40404908, 2025). "Genetic ablation of TLR2, TLR4, and TLR9 in K‐ras‐driven lung adenocarcinoma leads to a reduction of tumor burden, angiogenesis, and tumor cell proliferation." (PMID 40727252, 2025). "As discussed in Section 2 and Section 3, receptors such as TLR2, TLR4, TLR7, TLR9 and NLRP3 generally promote tumor progression and immune suppression." (PMID 41157253, 2025). "These systems can also be leveraged to reprogram macrophages, enhancing the stability of METTL14 in vivo, inhibiting the TLR4 pathway, regulating macrophage polarization, and remodeling the TME to improve anti-tumor responses." (PMID 40380260, 2025). "Lipopolysaccharides (LPS) present on the surface of H. pylori act as ligands for Toll-like receptor 4 (TLR4), triggering the activation of downstream signaling molecules, including NF-κB, leading to inflammation and subsequent tumor formation." (PMID 40927726, 2025). "Studies suggest that MO extracts possess anticancer activity by modulating apoptosis, inhibiting tumor cell proliferation, and interacting with key signaling pathways, including YAP/TAZ, Nrf2-Keap1, TLR4/NF-κB, and Wnt/β-catenin." (PMID 40149610, 2025). "Fusobacterium nucleatum exacerbates CRC progression by activating Toll-Like Receptor 4 (TLR4)/nuclear factor-κB (NF-κB) signaling and upregulating microRNA-21 expression, thereby increasing CRC cell proliferation and tumor burden in murine models." (PMID 40452858, 2025). "The expression profiles of IL1β, IL10, IL18, TNF-α, TLR4, GATA3, and CD68 in HHV-infected PCa FFPE biopsies indicated an inflammatory environment conducive to immune alteration and potential tumour progression." (PMID 40430084, 2025). "In lung cancer, silencing TLR2, TLR4, and TLR9, along with epithelial-specific MyD88/NF-κB signaling, significantly reduces the expression of pro-tumor immunosuppressive factors like RETNLB, while enhancing the expression of anti-tumor cytokines like IFN-γ." (PMID 41200171, 2025). "We demonstrated a significant increase in TLR4 immunostaining on IBC cells and adjacent non-tumor tissues." (PMID 40647480, 2025). "HMGB1 plays a crucial role in initiating neutrophil pro-tumor activation, interacting with TLR4 to activate the TNF-β pathway and induce autophagy and pro-tumor activation of neutrophils via HMGB1/TLR4/NF-κB signaling." (PMID 40108630, 2025). "The therapeutic potential of this mechanism has been demonstrated in OS models, where administration of synthetic TLR4 agonists reprogrammed M2 TAM to the M1 phenotype, leading to tumor regression and inhibition of metastasis." (PMID 41516196, 2025). "In another study, TLR4 recognized LPS and directly activated c-Jun N-terminal kinase (JNK)/MAPK signaling to improve epithelial-mesenchymal transition (EMT), tumor cell invasion, and metastasis." (PMID 40185720, 2025). "For example, TLR-4 activation leads to an increase in substances like interleukin-6 (IL-6) and tumor necrosis factor-alpha (TNF-alpha), which can help tumor growth." (PMID 40727443, 2025).
tumor (continued). "The observed Eftud2 overexpression mediates the alternative splicing of components of the Toll-like receptor-4 (TLR4)-MyoD88 pathway required for the activation of NF-κB signalling, which promotes both chronic intestinal inflammation and tumour progression." (PMID 39858001, 2025). "Subsequent advancements in this formulation were achieved by incorporating two distinct adjuvants (i.e., TLR4 and TLR9 agonists) and protein antigens, resulting in robust anti-tumor efficacy in multiple murine tumor models." (PMID 40507963, 2025). "Toll-like receptor 4 (TLR4) signaling enhances proinflammatory cytokine production through NF-κB activation, shaping a tumor-permissive milieu." (PMID 41383623, 2025). "However, whether TLR4 is expressed by NSCLC tumor cells and activated by LPS remains unclear." (PMID 40817754, 2025). "For instance, in brain cancers like glioma, activation of TLR2, TLR4, and TLR9 promotes tumor growth and metastasis by modulating signaling pathways such as NF‐κB and MAPK." (PMID 40922674, 2025). "In this study, Indocyanine green (ICG), a photosensitizer and Monophosphoryl lipid A (MPLA), a Toll-like receptor 4 agonist, were encapsulated into the core of PEG-PLGA nanocarrier, and the surface was further modified with tumor-targeting peptide TMTP1." (PMID 40487160, 2025). "For Example, Fusobacterium nucleatum is known to activate pro-inflammatory pathways via Toll-like receptor 4 (TLR4), which can foster an environment conducive to tumor growth." (PMID 40871467, 2025). "PEI, a cationic organic polymer, has been reported as a ligand for TLR4 and TLR5 and is known to enhance the immunogenicity of tumor vaccines." (PMID 40291558, 2025). "Radiation-induced HMGB1 release from dying cells activates Toll-like receptor 4 (TLR4)-dependent DCs, which in turn mediate a cytotoxic T-lymphocyte (CTL) response against tumor cells." (PMID 40598513, 2025). "Elevated expression of TLR1, TLR2, TLR4, TLR5, TLR6, and TLR9 has been detected in GBM, particularly within the mesenchymal subtype with significant impact in tumor progression." (PMID 41157253, 2025). "Overexpression of TLR4 significantly enhances TLR4/Myd88/NF-κB/PD-L1 signaling and the apoptosis of CD8 + T cells, thereby facilitating tumor cell immune escape and reversing the regulatory effects induced by LINC00886 downregulation." (PMID 40999508, 2025). "Exhibits anti-tumor and anti-neuroinflammatory effects in a GPX4-dependent manner through the TLR4/NF-κB pathway." (PMID 40153574, 2025). "Toll-like receptors (TLRs), including TLR2, TLR4, TLR7, TLR8, and TLR9, are critical pattern recognition receptors on TAMs, with diverse ligands such as tumor proteins, acute-phase proteins, drugs, and bacterial metabolites." (PMID 40948759, 2025). "Combined inhibition of TLR4 and SPHK1 synergizes with TMZ to suppress tumor growth and reverse M2 macrophage polarization in vivo, highlighting the therapeutic promise of targeting the ENO1/TLR4-SPHK1 axis." (PMID 41353343, 2025). "Immune evasion was evident through upregulation of NFKB1, IFNAR1, TLR4, IL1A/B/R1, and NOS2, facilitating tumour escape from immune surveillance." (PMID 41007296, 2025). "Studies have found that aging PC cells can alter the tumor microenvironment by releasing high mobility group box 1 (HMGB1), one of the specific ligands of TLR-4." (PMID 40404908, 2025). "IHC was used to detect the protein expression levels of TLR4 and 8 in the lung tissues of NSCLC cases and in non-tumor samples (controls)." (PMID 40025339, 2025). "Alternately activated (M2) macrophages promote tumor growth and invasiveness in HCC, and stimulate HCC cell migration and epithelial-mesenchymal transition through the TLR4/STAT3 signaling pathway." (PMID 38318171, 2024). "M1-like macrophages can counteract HCC progression by modulating the tumor microenvironment, whereas M2-like macrophages can promote HCC cell proliferation and invasion by activating the TLR4/STAT3 signaling pathway." (PMID 39091612, 2024).